ATF1 (activating transcription factor 1)
Diseases named in the same sentence as ATF1 in open-access papers (continued):
Sharing a sentence is not in itself a finding about the gene and the disease.
sarcoma (continued). "Second, the expression of wt ATF1 is retained in CCS, in contrast to several sarcomas driven by fusion proteins containing EWSR1, in which expression of the wt form of the EWSR1 fusion partner is lost." (PMID 35477713, 2022). "We found Creb/Atf and Jun/Fos motifs as the most enriched motifs in both sarcoma-specific and MEF-specific binding sites, which is consistent with the fact that EWS/ATF1 binds to the genome through the DNA-binding domain of ATF18." (PMID 31488818, 2019). "Therefore, we compared sarcoma cells (G1297) and sarcoma-iPSC MEFs, two different cell types that share genetic abnormalities, which are associated with sarcoma development but exhibit opposing senescence responses and cellular kinetics after EWS/ATF1 induction." (PMID 31488818, 2019). "To further investigate the effect of EWS/ATF1 expression on OIS in sarcoma-iPSC-derived differentiated cells, we established mouse embryonic fibroblasts (MEFs) from sarcoma-iPSC chimeric embryos, which was followed by puromycin selection." (PMID 31488818, 2019). "We focused on H3K27ac, an active epigenetic mark, in sarcoma cells (G1297) and MEFs before EWS/ATF1 induction." (PMID 31488818, 2019). "The senescence-associated β-galactosidase (SA β-gal)-positive cell ratio was significantly higher in EWS/ATF1-expressing MEFs than in non-expressing MEFs, suggesting that EWS/ATF1 induces premature senescence in sarcoma-iPSC MEFs." (PMID 31488818, 2019). "We found that Tppp3-expressing cells can give rise to sarcomas and early sarcoma lesions often express S100, which suggests that Tppp3/S100-expressing neural crest-derived cells in peripheral nerves are a cell of origin for EWS/ATF1-induced sarcomas." (PMID 31488818, 2019). "Collectively, we concluded that Tppp3-expressing cells, but not Sox10-expressing cells, are a cell of origin for EWS/ATF1-induced sarcomas." (PMID 31488818, 2019). "We next examined secondary sarcoma development in sarcoma-iPSC chimeric mice by inducing EWS/ATF1." (PMID 31488818, 2019). "Notably, in sharp contrast to the active proliferation of EWS/ATF1-expressing sarcoma cells, EWS/ATF1-expressing sarcoma-iPSC MEFs ceased growth and changed morphology into a large and flat shape." (PMID 31488818, 2019). "Furthermore, Ink4a and Arf expressions were rapidly increased after the withdrawal of EWS/ATF1 in sarcoma cells, demonstrating that EWS/ATF1 expression actively prevents senescence in sarcoma cells." (PMID 31488818, 2019). "Indeed, CCS is a sarcoma subtype, and the characteristic EWS/ATF1 translocation, resulting in the chimeric protein EWS/ATF1, is responsible for the melanocytic differentiation." (PMID 22693489, 2012). "Notably, we here show that sarcoma-iPSC mice immediately develop secondary sarcomas from peripheral nerve cells, but exhibit premature senescence in other tissues upon the induction of EWS/ATF1." (PMID 31488818, 2019). "Correlation analysis of CNVs from CCLE with drug-response data of CTRP in 27 sarcoma cell lines, 33 CNVs out of 63 genes correlated with either sensitivity or resistance to 17 chemotherapies from which actionable CNV signatures such as IGF1R, MYC, MAPK1, ATF1, and MDM2 were identified." (PMID 30704460, 2019). "However, other Cre alleles failed to induce sarcomas, suggesting that cells expressing well-established markers for differentiated neural crest derivatives do not give rise to sarcomas after EWS/ATF1 induction." (PMID 31488818, 2019). "In this study, they included CIC::DUX4, BCOR-altered, EWSR1::ATF1/CREB1, and YWHAE::NUTM2B sarcomas, as well as fusion-negative SRCSs, reflecting the expanding molecular landscape within this spectrum." (PMID 41514642, 2025).
sarcoma (continued). "Case 10 tested negative for ES and Ewing-like tumours (CIC sarcoma and NFATC2-reaarranget tumour), but targeted NGS revealed a fusion between EWSR1 and ATF1." (PMID 36614077, 2022). "ChIP-Seq data for H3K27ac in both Dox OFF sarcoma cells (sarcoma cells without EWS/ATF1 expression) and wild-type MEFs28,29 revealed that EWS/ATF1 was recruited to H3K27-pre-marked regions in both sarcoma cells and sarcoma-iPSC MEFs." (PMID 31488818, 2019). "In contrast, sarcoma-iPSC mice that were not given Dox were vigorous and did not develop any CCS-like sarcomas even at 6 months of age (n = 7), except for one mouse that developed EWS/ATF1-independent rhabdomyosarcoma." (PMID 31488818, 2019).
melanoma (30 papers, 2003 to 2025). A malignant, usually aggressive tumor composed of atypical, neoplastic melanocytes. "Overexpression of ATF1 is also associated with the upregulation and expression of matrix metalloproteinase 2, contributing to metastatic phenotype in both nasopharyngeal carcinoma and melanoma cells." (PMID 39769457, 2024). "ATF1 is overexpressed in various types of cancer, including lymphomas, nasopharyngeal carcinoma, and melanoma." (PMID 36251702, 2022). "ATF1 was found to be over-expressed in several cancer types including lymphoma, melanoma and nasopharyngeal carcinoma, and functioned as a tumor promoter both in vitro and in vivo." (PMID 29445242, 2018). "ATF1, a negative regulator of apoptosis, is upregulated in metastatic melanoma cells, and inactivation of ATF1 in melanoma cells resulted in inhibition of tumor growth and metastasis in vivo." (PMID 28800781, 2017). "EWS is fused to ATF1 (activating transcription factor 1) in malignant melanoma of soft parts, WT1 (Wilms tumor 1) in intra-abdominal DSRCT, CHOP in myxoid liposarcoma, and CHN in myxoid chondrosarcoma." (PMID 20924475, 2010). "CCS was originally thought to be melanoma due to its melanocytic differentiation characteristics, likely due to the expression of genes of melanin metabolism driven by the EWSR1::ATF1 chimera." (PMID 39769457, 2024). "For example, PAF triggers human melanoma cells via stimulating the phosphorylation of cAMP-responsive element (CRE)-binding protein (CREB) and activating transcription factor-1(ATF-1)." (PMID 36297097, 2022). "In human melanoma, CREB and ATF-1 have been reported to act as survival factors and favour tumour growth and metastasis." (PMID 34947968, 2021). "Despite its similarity with melanoma, CCS is a distinct entity genetically characterized by the presence of a chromosomal translocation involving EWSR1 most frequently partnered with ATF1." (PMID 20598147, 2010). "Although CCS has pathobiological similarities with melanoma, the EWS/ATF1 fusion gene, which characterizes most CCS, may lead to distinct molecular differences." (PMID 38434963, 2024). "CREB protein levels positively correlate with the metastatic potential of melanoma cells and although ATF-1 is not identified in normal human melanocytes, it is easily identifiable in metastatic melanoma." (PMID 24690670, 2014). "This specific rearrangement of the EWSR1/ATF1 genes serves as a defining genetic feature of CCSST, setting it apart from malignant melanoma, where such rearrangement is notably absent." (PMID 38755643, 2024).
breast carcinoma (14 papers, 2013 to 2025). "In agreement, high phospho-CREB1/ATF1 intensity is associated with poor overall survival and disease-free survival in breast cancer (P = 0.007 and P < 0.001, respectively)." (PMID 37463926, 2023). "The polymorphic site, ATF1 rs11169571, was analyzed in a group of ovarian/breast cancer patients with BRCA1 or BRCA2 mutation." (PMID 30905073, 2019). "Moreover, depletion of ATF1 in primary breast cancer cells confirms that ATF1 deficiency abrogates the sphere formation in all of the four primary cancer cells." (PMID 37463926, 2023). "Further characterization of this new association in breast cancer revealed that MC1R promotes breast cancer cell proliferation by signaling through the MC1R-cAMP-CREB/ATF-1 and MC1R-ERK-NFκB axes, resulting in accelerated progression of the cells from the G1 to the S phase of the cell cycle." (PMID 37679505, 2023). "MC1R signaling accelerates G1/S phase progression and promotes breast cancer progression through the cAMP-CREB/ATF-1 and ERK-NFκB pathways." (PMID 40547309, 2025). "The role of ATF1 in breast cancer has been identified as a tumor suppressor, including its activation by BRCA1, increasing transcription of MHC class genes and its involvement in regulating the steroidal hormone synthesis (Haakenson, Kester & Liu, 2012)." (PMID 37810779, 2023). "The nominally significant SNPs included colorectal cancer GWAS SNPs in SMAD7, C11orf93, SCG5, and ATF1, and breast cancer SNPs related to CDKN2B-AS1, FGFR2, GDI2, CDYL2." (PMID 29698419, 2018). "Moreover, Cox repression indicates that phospho-CREB1/ATF1 intensity is an independent factor in determining disease-free status in breast cancer (P < 0.001)." (PMID 37463926, 2023). "These include EMT (TWIST1, SNAIL1, RUNX1, RUNX2, HIF1, and NOTCH1), breast cancer maintenance (OCT4, SP1, GATA1, ATF1, FOXO3a, ELK1, VDR, and NRF1), pro-metastatic responses (SMAD2/3, HNF1a, GLI1, NANOG, YY1, MYB1, and AP1), and immune modulation (STAT1/3)." (PMID 38398186, 2024). "These suggested that active MC1R signaling through two signaling pathways, the MC1R-cAMP-CREB/ATF-1 and the MC1R-ERK-NFκB pathways, controlled growth and proliferation in breast cancer cells." (PMID 37679505, 2023). "Mechanistically, MC1R signaling through the MC1R-cAMP-CREB/ATF-1 and MC1R-ERK-NFκB axes accelerated the G1-S transition in breast cancer cells." (PMID 37679505, 2023). "This suggested that MC1R signaling through the MC1R-cAMP-CREB/ATF-1 and MC1R-ERK-NFκB axes promotes cell cycle progression and accelerates cell proliferation in breast cancer cells." (PMID 37679505, 2023). "Notably, CRE activity (ssGSEA scores of CREB1/ATF1 target gene set) is positively correlated with neural signals in both TCGA (pan-cancer) and METABRIC (breast cancer) datasets (r = 0.4777 and 0.4180 for TCGA and METABRIC, respectively)." (PMID 37463926, 2023). "Although neither NF-kappaBnor ATF-1 per se exhibits any specific tissue specificity, theNF-kappaB family has shown to be active in human breast cancers." (PMID 23924163, 2013). "Five hundred μg of proteins extract from MCF-7 and HCC1937 breast cancer cell lines were subjected to immunoprecipitation with a monoclonal antibody directed against the C terminus of BRCA1 (D9-Santa-Cruz), followed by immunoblotting with an anti-ATF1 antibody." (PMID 26061043, 2015).
angiomatoid fibrous histiocytoma (13 papers, 2012 to 2025). "Furthermore, although EWSR1::ATF1 is associated with multiple tumors, including angiomatoid fibrous histiocytoma, myoepithelial tumors, hyalinizing clear cell carcinoma, and CCS-like tumors of the gastrointestinal tract, SOX10 expression is relatively specific to CCS." (PMID 37405123, 2023). "Similarly, low split signals for CREB1 and ATF1 lowered the possibility of angiomatoid fibrous histiocytoma." (PMID 34797454, 2021). "Specifically, MAP3K8 and ALK presented PAX8+ papillary proliferations, ESWR1/FUS::ATF1 and EWSR1::YY1 displayed angiomatoid fibrous histiocytoma-like patterns, while SUFU showcased ‘tissue culture’-like spindle cell proliferation." (PMID 39059063, 2024).
Ewing sarcoma (11 papers, 2007 to 2023). A small round cell tumor that lacks morphologic, immunohistochemical, and electron microscopic evidence of neuroectodermal differentiation. "Fluorescence in situ hybridization revealed Ewing sarcoma breakpoint region 1 rearrangement and Ewing sarcoma breakpoint region 1-activating transcription factor 1 fusion." (PMID 37352028, 2023). "Fusion of ATF1 with the Ewing’s Sarcoma gene, or with FUS, results in continuous signaling and sarcomatous tumour formation." (PMID 26553438, 2015). "ChIP-sequencing of V5-EWSR1::ATF1 identified previously unreported motifs including the AP1 motif and motif comprised of TGA repeats that resemble GGAA-repeating microsatellites bound by EWSR1::FLI1 in Ewing sarcoma." (PMID 38136296, 2023).
clear cell carcinoma (10 papers, 2018 to 2025). "In hyalinizing clear cell carcinoma, ATF1 could fuse with EWSR1 and was associated with tumor development." (PMID 35568813, 2022).
colorectal cancer (10 papers, 2016 to 2022). A primary or metastatic malignant neoplasm that affects the colon or rectum. "The ATF1 rs11169571 variant was shown to be strongly related to ATF1 expression by influencing hsa-miR-1283 and hsa-miR-520d-5p binding, which may increase susceptibility to colorectal cancer." (PMID 36428729, 2022). "However, other studies have shown that ATF1 acts as a tumor suppressor in breast and colorectal cancer." (PMID 36251702, 2022). "It was speculated that ATF1 is involved in human colorectal cancer cell proliferation through the p300-MYB-CREB axis." (PMID 34820188, 2021). "Moreover, LINC00665 could promote the progression of colorectal cancer by regulating the miR-9-5p/ATF1 axis." (PMID 35251139, 2022). "While the exact contributions of ATF1, DUSP10 and CASC8 in TA remain to be further elucidated, our findings further support that genes involved in colorectal cancer may also be involved in tooth development and provide additional insights into deciphering the complex etiology of the condition." (PMID 29445242, 2018).
hepatocellular carcinoma (7 papers, 2011 to 2025). A malignant tumor that arises from hepatocytes. "As recent studies have shown that ATF1 is OE in several cancers, including hepatocellular carcinoma, non-small cell lung cancer, esophageal squamous cell carcinoma, and cervical cancer, specific inhibitors for ATF1 are being developed." (PMID 40607797, 2025). "LncRNA GHET1 is activated by histone 3 lysine 27 (H3K27) acetylation and promotes hepatocellular carcinoma (HCC) tumorigenesis through regulating activating transcription factor 1 (ATF1)." (PMID 31885739, 2019). "Similar findings were reported for CREB-1 and ATF-1 in human hepatocellular carcinoma cells and human leukemia cells." (PMID 21760912, 2011). "Regulation of cAMP-PKA-CREB/ATF1 signaling represents a non-canonical function of CPS1, and targeting of the PKA-CREB/ATF1 axis may improve the therapeutic effects of aspirin in hepatocellular carcinoma." (PMID 35008510, 2021). "In hepatocellular carcinoma cells, AMPK acts upstream to drive the sAC–cAMP–PKA–CREB/ATF1 cascade, as shown in aspirin-treated models where AMPK activation increases cAMP and PKA activity, and AMPK knockdown abolishes this effect." (PMID 40943297, 2025).
myoepithelial tumor (7 papers, 2014 to 2025). A benign or malignant tumor characterized by the presence of cells that show myoepithelial differentiation. "FISH studies, performed to rule out the possibility of gastrointestinal clear cell sarcoma and a myoepithelial tumor, showed no rearrangement of the EWSR1, FUS, ATF1, and CREB1 genes." (PMID 35001360, 2022).
cervical carcinoma (6 papers, 2016 to 2025). A carcinoma arising from either the exocervical squamous epithelium or the endocervical glandular epithelium. "Reportedly, miR-409-3p is remarkably under-expressed in cervical cancer tissues and cells, and miR-409-3p overexpression specifically down-regulated the expression level of activating transcription factor 1, inhibiting cell growth, migration, invasion and glycolysis." (PMID 35264067, 2022). "Moreover, they found that ATF1 and RAS were among the 5 most expressed genes detected in circulating EVs, proposing them as diagnostic markers for cervical cancers." (PMID 34445131, 2021). "In a different study, ATF1 and RAS were found to be significantly elevated in tumors of primary and recurrent cervical cancer mouse models." (PMID 34445131, 2021). "Furthermore, there was a higher level of activating transcription factor 1 (ATF1) and RAS in tumors of the cervical cancer mouse model." (PMID 33671587, 2021).
colon cancer (6 papers, 2017 to 2025). "An additional novel dual-target inhibitor of RSK1/MSK2, APIO-EE-07, is used against colon cancer and inhibits cell proliferation through the downregulation of ATF1 expression and increased expression of Bax, caspase-3, and PARP." (PMID 40607797, 2025). "The MUC2 protein directly mediates Chk2/STAT3/CREB/ATF-1 signaling and E-cadherin expression in colon cancer." (PMID 40859234, 2025). "We performed qRT‐PCR and immunohistochemistry to detect mRNA and protein expression of ATF1, respectively, in normal mouse colons and AOM‐DSS‐induced colon tumors." (PMID 39582289, 2025). "Thus, we conclude that endogenous H2S/polysulfide biosynthesis by 3-MST in colon cancer cells promotes CyR61 mRNA induction, most likely through Sp1 sulfhydration, and through the activation of S1PR, ATF1 and CREB." (PMID 36113340, 2022). "We expected that the transcription factors WRNIP1, ATF1, CBFB, and NR2F6, as well as the microRNAs miR-1-3p, miR-26b-5p, miR-164a-5p, and miR-9-5p, would play essential roles in metabolic abnormalities of cells in obese people and the development of colon cancer." (PMID 37711894, 2023).
lung carcinoma (6 papers, 2020 to 2024). "In lung cancer, ATF1 expression was associated with metastasis, tumour stage and poor prognosis, and38 in oesophageal cancer, ATF1 expression was correlated with poor differentiation, lymph node metastasis and early tumour invasion." (PMID 33342045, 2021). "In lung cancer, activating transcription factor 1 (ATF1) promotes ferroptosis resistance by stabilizing PROM2 mRNA." (PMID 39624080, 2024). "The levels of ATF1/CREB1 in immortalized epithelial (MCF-10A) and a panel of breast, colon and lung cancer cells indicate the presence of ATF1 in multiple cancer types." (PMID 37463926, 2023). "The impaired sphere-forming efficiency in ATF1 deficient settings is verified in breast (SUM149, T47D), colon (DLD1) and lung cancer (A549 and H460) cells, indicating ATF1 as a conserved activator of cancer stemness." (PMID 37463926, 2023). "ATF1 led to the increasing level of MMP2 expression as well as promotion in lung cancer cell migration and invasion." (PMID 35397606, 2022). "Activated transcription factor 1 (ATF1) plays an important role in the migration and invasion of lung cancer cells." (PMID 33115469, 2020). "It had been described previously that the miR-340-5p/activating transcription factor 1 (ATF1) axis regulates the proliferation and invasion of lung-cancer cells." (PMID 35743055, 2022). "A study proposed that the silencing of ATF1 can induce the down-regulation of MMP2 expression, thereby inhibiting the migration and invasion of lung cancer cells." (PMID 33115469, 2020).
mesenchymal neoplasms (6 papers, 2019 to 2024). "Promiscuity of EWSR1::ATF1 fusions as well as the polyphenotypic phenotype of this tumor type may lead to diagnostic confusion with both mesenchymal and non-mesenchymal neoplasms." (PMID 39031200, 2024). "In summary, we described four extra-abdominal round cell/epithelioid mesenchymal neoplasms sharing EWSR1::ATF1 fusions, frequent expression of epithelial and neuroendocrine markers, occasional aberrant expression of ALK and MUC4, but not fitting with any currently defined mesenchymal neoplasm." (PMID 39031200, 2024). "Including our study, 10 unclassified mesenchymal neoplasms with epithelioid/round cell morphology and an EWSR1::ATF1 fusion have been reported." (PMID 39031200, 2024).